RYR2 (ryanodine receptor 2)
Diseases named in the same sentence as RYR2 in open-access papers (continued):
Sharing a sentence is not in itself a finding about the gene and the disease.
cancer (continued). "Mutations in SWI/SNF and chromatin-remodeling complex (SMARCA4, COL6A3, RYR2, and SPEG) contributed to cancer and neurological disorders." (PMID 31428092, 2019). "Under the differentially expressed genes we identified several genes previously related to cancer including the up-regulated SSX1, SSX2, RXFP2, RYR2 and the down-regulated CSTA, TSPAN7, NEO1, S100A, SERPINB5 and SEPP1." (PMID 25857299, 2015). "RYR2 may be more expressed than RYR1 and RYR3 in tissues such as lung and gastrointestinal organs and tract, where the incidence of cancers is high, and this may lead to the identification of more mutations predominantly in RYR2 than RYR1 or RYR3." (PMID 36167878, 2022). "Interestingly, TCI revealed functional impact of certain SGAs with very high alteration frequencies, such as TTN, CSMD3, MUC16, RYR2, LRP1B, and ZFHX4, whose roles in cancer development remain controversial." (PMID 31276486, 2019). "High RyR2 expression in cardiomyocytes leads to spontaneous Ca2+ leakage from ER, and subsequent diminished systolic Ca2+ transients which are not necessary for cancer cells." (PMID 36453019, 2023). "We also found that some of the identified genes, including TTN, MUC16, CSDM3, RYR2, USH2A, and SYNE1, are only altered in gynecological malignancies and not in other cancer types, highlighting their specific role in driving gynecological malignancies." (PMID 32626534, 2020).
tumor (37 papers, 2011 to 2025). "In LUAD, RYR2 is associated with a high tumor mutation burden and serves as an independent risk factor for patient prognosis." (PMID 40200715, 2025). "The findings demonstrate the importance of the pathological stage and tumor size in the genetic association between the expression of the RYR2 gene and OSCC." (PMID 39408657, 2024). "Since RYR2 is a huge gene with sporadic mutations and a lower expression in tumor tissues than adjacent tissues in ESCC, it is difficult to carry out ectopic overexpression." (PMID 36168622, 2022). "For BC, RYR2 mutation was found to be correlated with a decreased BC risk restricted by PR, ER, and tumor stage." (PMID 34888385, 2021). "According to the CIBERSORT algorithm, we further assessed the association between RYR2 mutation and tumor-infiltrating immune cells in the BC microenvironment." (PMID 34888385, 2021). "Meanwhile, patients with RYR2 mutation suggested an “immune-hot” tumor, which enriched abundant immune-related pathways, numerous immune cell infiltrations, and higher expression of ICPs." (PMID 34079583, 2021). "Collectively, these results suggest that the expression and localization of RYR2 might affect its biological functions and that RYR2 might be associated with tumor progression." (PMID 36168622, 2022). "However, current studies had revealed a correlation of RYR2 mutation with immune cells and tumor progression." (PMID 36578478, 2022). "Several studies uncovered that RYR2 mutation played a positive side in tumor prognosis." (PMID 35975176, 2022). "It will also be interesting to explore whether RyR2 regulates spatiotemporal Treg interactions with other cell types, including B cells, tumor-associated myeloid populations, and stem cells, to promote Treg function in different inflammatory contexts or microenvironments." (PMID 38099491, 2023). "Thus, we speculate that RYR2 mutation with a high TMB in BC might drive the immune system to scavenge tumor cells." (PMID 34888385, 2021). "In conclusion, our findings highlight RYR2 as a tumor suppressor in LUAD via inducing mitochondrial dysfunction and immune cell infiltration." (PMID 40200715, 2025). "Both mRNA and protein levels of RYR2 are reduced in LUAD tumor samples compared to adjacent non‐tumor tissues." (PMID 40200715, 2025). "In this study, we identified that tumors with higher RYR2 expressions had “hot” phenotype with reduced tumor purity and increased immune cell infiltration." (PMID 40200715, 2025). "In this study, we examined the expression levels of RYR2 in tumor and adjacent non‐tumor samples from patients with LUAD." (PMID 40200715, 2025). "We further evaluated the functional roles of RYR2 in tumor cells and tumor microenvironments to elucidate its potential impact on LUAD progression and therapy." (PMID 40200715, 2025). "RYR2 level was negatively correlated with tumor purity and positively correlated with the infiltration of B cells, CD4+ T cells, CD8+ T cells, neutrophils, macrophages, and dendritic cells." (PMID 40200715, 2025). "In conclusion, our study reveals that RYR2 functions as a tumor suppressor in LUAD by inducing mitochondrial dysfunction and promoting immune cell infiltration." (PMID 40200715, 2025). "We adoptively transferred Pmel T cells transduced with either control shRNA or Ryr2 shRNA (referred to as Pmel-Ryr2KD cells) into mice bearing B16-F10 melanoma tumor." (PMID 38451948, 2024). "In conclusion, our experimental results confirm an association between SNP rs2779359 in the RYR2 gene and OSCC, as well as with advanced pathological stages and large tumor sizes." (PMID 39408657, 2024). "Dysregulated FGFR4 activates the AKT/RYR2 axis, leading to tumor proliferation, invasion, and altered lipid metabolism in TNBC." (PMID 39658878, 2024).
tumor (continued). "Mechanically, we revealed that dysregulation of FGFR4 led to activation of the AKT/RYR2 axis and the following tumor proliferation, invasion, and lipid metabolism reprogramming in TNBC." (PMID 39658878, 2024). "This is evidence that RyR2 expression in tumor cells was closely related to metastasis behavior of CRC." (PMID 36453019, 2023). "In MC38 tumor model, the infusion of both Tregs and Ryr2–/– Tconvs facilitated the tumor growth, with control Tconvs showing no overt effects." (PMID 38099494, 2023). "RYR2 tended to express more in the cytoplasm, while only a subset of tumor tissues had evident nuclear staining of RYR2." (PMID 36168622, 2022). "We also found a lower expression level of RYR2 in tumor tissues than in the adjacent healthy counterparts." (PMID 36168622, 2022). "The expression of RYR2 was remarkably decreased in tumor tissues than in the adjacent normal tissues." (PMID 36168622, 2022). "In tumor cells alteration of RYR2 regulated intracellular Ca2+ levels promotes angiogenesis and cellular migration thus confirming its critical role in tumor growth and progression." (PMID 32626534, 2020). "In OSCC, RYR2 gene expression correlated with clinical stage and tumor size." (PMID 39408657, 2024). "We next performed an analysis to determine whether RYR2 SNPs could be associated with OSCC patient characteristics such as clinical stage, tumor size, lymph node metastases, distant metastases, and cell differentiation." (PMID 39408657, 2024). "Considering the alleviation of T cell exhaustion upon genetic knockdown of Ryr2, we next checked whether inhibiting it would improve the anti-tumor potential of T cells." (PMID 38451948, 2024). "As shown in the waterfall plot, there are variations in the tumor mutational burden (TMB) of two subtypes, and the frequencies of TTN, CSMD3, MUC16, RYR2, LRB1P and ZFHX4 mutations in the high-risk group were considerably higher than those in the low-risk group." (PMID 38345559, 2024). "TMB in the tumor tissues with mutated RYR2 (n = 5) was much higher than that in non-mutated RYR2 (n = 38) (p < 0.001)." (PMID 37038181, 2023). "In addition, we performed the expression profiles of significantly mutated genes in one normal group and two tumor groups; we identified 20 DEGs; among them CSMD3, DCHS2, LRP2, RYR2, and ZFHX4 were significantly negatively correlated with PFS." (PMID 35975176, 2022). "Interestingly, tumor tissues with cytoplasm and nuclear staining of RYR2 showed a higher expression level of RYR2 than the tissues with only cytoplasmic expression (0.001)." (PMID 36168622, 2022). "More interestingly, serial tumor profiling also allowed us to identify a panel of mutated genes enriched and present at baseline and persisting through the end of CRT including FBXW7, LRP1B, and RYR2." (PMID 36201462, 2022). "Although generally considered a passenger, RYR2 was found to have low expression in tumor tissues." (PMID 36168622, 2022). "Thus, we suggest that the change in tumor-infiltrating immune cells induced by RYR2 contributes to antitumor immunity in BC." (PMID 34888385, 2021).
tumor (continued). "Only two mutations, RANBP2 P1380R in BLCAb001, and RYR2 E1859K in BLCAb002, were present in the PDXs but not in the primary tumor." (PMID 27823983, 2016). "Although the authors did not report on the impact of RyR2 overexpression in a tumor model, increasing RyR2 activity may decrease Treg suppressive function and enhance DC-mediated activation of Tconvs in the tumor microenvironment, where Tregs frequently impede antitumor immunity." (PMID 38099491, 2023). "Additionally, the localization of RYR2 also varied in tumor tissues." (PMID 36168622, 2022). "In addition, we performed the expression profiles of significantly mutated genes between the normal group and tumor groups and identified 20 differentially expressed genes (DEGs); among them, CSMD3, DCHS2, LRP2, RYR2, and ZFHX4 were significantly negatively correlated with PFS." (PMID 35975176, 2022). "First, due to the lack of clinical data in the ICGC database, we could not determine whether RYR2 mutations are also associated with prognosis and tumor immunity in European Union patients." (PMID 34888385, 2021). "To confirm these findings, we performed IHC on tumor samples from 38 LUAD patients and stratified them into two groups based on RYR2 expression." (PMID 40200715, 2025). "Knockdown of RyR2 or inhibition of AKT in CD8+ T cells maintained TCF1 levels, induced a sustained anti-tumor response, and enhanced responsiveness to anti-PD1 therapy." (PMID 38451948, 2024). "We found the co-occurrence of genetic mutations in tumors with PARP1 alterations to be involved with some genes such as KMT2D/2C as driver genes, PIK3CA, ARID1A, H3F3A, HIST3H3, RYR2, and thus, PARP1 alteration should promote tumor mutability." (PMID 34531868, 2021). "In an RYR2-positive prostate cancer cell line, RYR-related Ca2+ mobilization augments tumor cell apoptosis." (PMID 34888385, 2021). "In this study, we obtained transcriptomic data (normal n = 59, tumor n = 541) from TCGA portal and RYR2 protein abundance data from cProSite, which includes 86 normal and 91 tumor samples." (PMID 40200715, 2025). "Importantly, RyR2 expression was significantly upregulated in CRC patients with tumor serosa invasion (P = 0.0049) and intratumoral vascular tumor thrombus (P = 0.0155)." (PMID 36453019, 2023). "Notably, RYR2 levels exhibited a negative correlation with tumor purity, and tumors with lower RYR2 levels showed diminished infiltration of T cells and dendritic cells." (PMID 40200715, 2025). "In m6A-TSHub, a total of 184,554 and 499,369 m6A sites derived from 23 normal human tissues and 25 matched tumor samples were collected (m6A-TSDB), from which some potential patterns for the tissue-specific m6A modification sites were revealed (e.g., heart-enriched genes RYR2 and PXDNL)." (PMID 36096444, 2023).
cardiovascular disease (15 papers, 2014 to 2025). "A number of clinical conditions related to cardiovascular disease including DCM are caused by genetic mutations in genes (e.g. RYR2) that control calcium release from the sarcoplasmic reticulum." (PMID 27548259, 2016). "The ryanodine receptor 2 (RYR2) gene is implicated in CPVT but may also be involved in other cardiovascular diseases." (PMID 37600027, 2023). "Similarly, RYR2, which contains rs1391189881 (log-p value ≥ 3), has been linked to 60 different cardiovascular disorders (Supplementary S4 and S6)." (PMID 35629146, 2022). "It is well known that increased oxidative stress in cardiovascular disease enhances RyR2 activity through reversible posttranslational modifications such as oxidative modifications and CaMKII (Ca /calmodulindependent protein kinase II)-dependent phosphorylation." (PMID 37598173, 2023). "To conclude, ER stress and the UPR can exacerbate SR Ca2+ mishandling via RyR2 and SERCA2a in cardiovascular disease and contribute to Ca2+-dependent arrhythmogenesis, through dysregulated SR oxidative status, perturbed luminal protein-protein interactions and protein homeostasis." (PMID 36425292, 2022). "In addition, RyR2 channels play an important role in glucose homeostasis and development of cardiovascular disease." (PMID 30170545, 2018). "Of the top 50 up-regulated hCM-specific genes we analyzed, 27 of them (54%) showed associations with at least one known cardiovascular diseases and 5 of them (NPPB, TNNT2, NPPA, RYR2, and PLN) were linked to more than 10 different types of cardiovascular diseases." (PMID 24474197, 2014). "Through the regulation of ER calcium release mediated by RyR2, a novel mechanism for PNS in the prevention of cardiovascular diseases is thereby identified." (PMID 31616293, 2019).
myopathies (6 papers, 2021 to 2025). "The NTR hosts numerous mutations linked to skeletal (RyR1) and cardiac (RyR2) myopathies, highlighting its potential as a therapeutic target." (PMID 34793835, 2022). "However, paralogs of myopathy genes are often expressed in different tissues, such as RYR1 and CASQ1, which are expressed in skeletal muscles, whereas RYR2 and CASQ2 are expressed in cardiac muscles." (PMID 39945189, 2025).
genetic diseases (4 papers, 2017 to 2022). "CPVT comprises heterogeneous genetic diseases, including mutations in ryanodine receptor type 2 (RyR2), calsequestrin 2 (CASQ2), triadin, or calmodulin." (PMID 28219898, 2017). "Here, we demonstrate that perturbed NTD tetramerization is a common molecular mechanism operating in RyR1 and RyR2 genetic disease." (PMID 36311249, 2022).
neurodegenerative disease (3 papers, 2020 to 2024). A disorder of the central nervous system characterized by gradual and progressive loss of neural tissue and neurologic function. "Furthermore, RYR2 (Ryanodine Receptor 2) dysfunction is linked to altered autophagic flux and neurodegenerative diseases like Alzheimer’s, impacting Ca2+ release." (PMID 39730725, 2024). "Furthermore, our data underpin the importance of RyR2-associated compensatory mechanisms for neurodegenerative diseases in which RyR2 downregulation has been reliably observed." (PMID 32641776, 2020). "Along these lines, the dendritic structural sparsification that we found in response to RyR2 deletion was reliably observed in both, human neurodegenerative diseases and animal models." (PMID 32641776, 2020). "Interestingly, the compensatory changes we found on the level of cellular excitability, neuronal morphology, spatial neuronal tuning and memory resemble the pattern of pathological changes seen in several neurodegenerative diseases in which changes of RyR2 have been described." (PMID 32641776, 2020).
neurological disorders (3 papers, 2019 to 2023). "We first became interested in neurological diseases for the simple reason that the identical RyR1 and RyR2 channels present in skeletal and cardiac muscles, respectively, are also expressed in different regions of the brain." (PMID 36647824, 2023).
infection (2 papers, 2015 to 2026). The state of being infected such as from the introduction of a foreign agent such as serum, vaccine, antigenic substance or organism. "After 12 weeks of infection, RyR2 protein levels remained unchanged (p > 0.05)." (PMID 41516391, 2026). "Treating HIV-1-infected animals with DTG/TDF/FTC for eight weeks, starting four weeks post-infection, also did not alter the expression of RyR2, but its phosphorylation at Ser2808 remained 2-fold higher than that of uninfected controls." (PMID 41516391, 2026).
autosomal dominant disease (1 paper, 2026). Autosomal dominant form of disease. "CPVT is generally an autosomal dominant disease and is associated with mutations in the RYR2 (ryanodine receptor/calcium release channel) gene and the recessive form is associated with mutations in CASQ2 (calsequestrin)." (PMID 41062843, 2026).
peripheral neuropathy (1 paper, 2023). A disorder affecting the peripheral nervous system. "Our model also accounts for the efficacy of commonly-used treatments of CVS, including mitochondrial-targeted therapies, propranolol (beta blockade interferes with catecholamine-induced release of calcium via the RYR2 calcium channel, and amitriptyline (used for peripheral neuropathy)." (PMID 37234784, 2023).
respiratory diseases (1 paper, 2013). "Network and functional ontology analyses revealed that RYR2 is an integral part of dermatological or allergic disorder biological networks, specifically in the functional classes involving inflammatory, eosinophilic, and respiratory diseases." (PMID 23829686, 2013).
RYR2 also shares sentences with these, for which no sentence is quoted: cardiac arrhythmias (66 papers); Brugada syndrome (7); long QT syndrome 3 (4); left ventricular noncompaction (3); metabolic disorders (3); skeletal muscle disorder (3); torsades de pointes (3); acute myocarditis (2); atrioventricular block (2); Cerebral ischemia (2); childhood asthma (2); developmental delay (2); endothelial dysfunction (2); familial atrial fibrillation (2); gastric cancer (2); hepatocellular carcinoma (2); Impaired glucose tolerance (2); infarction (2); iron deficiency (2); lung squamous cell carcinoma (2); Myocardial fibrosis (2); sarcopenia (2); skeletal myopathies (2); thyroid (2); ventricular extrasystoles (2); acute kidney injury (1); Adams-Oliver syndrome 5 (1); adenocarcinoma (1); age-related macular degeneration (1); amnesia (1).
A further 83 diseases each share a sentence with RYR2 in 1 paper.